LOX (lysyl oxidase)
Diseases named in the same sentence as LOX in open-access papers (continued):
Sharing a sentence is not in itself a finding about the gene and the disease.
clear cell renal cell carcinoma (9 papers, 2012 to 2025). "The top gene we identify is LOX, which is an oncogene implicated in clear cell renal cancer." (PMID 23365541, 2012). "In clear cell renal cell carcinoma, both miR-141-3p and miR-145-5p directly bind to the 3′ untranslated region of the LOX mRNA and cooperatively downregulate LOX expression, thereby suppressing the progression of clear cell renal cell carcinoma." (PMID 28036074, 2016). "miR-149 expression has a direct correlation with KCNMA1 and LOX oncogenes in clear cell renal cell carcinoma." (PMID 23527086, 2013). "Furthermore, integrin β1 or β3 mediated mechanotransduction is correlated with LOX expression in clear cell renal cell carcinoma and LOXL2 expression in fibroblasts, respectively, and is known to activate the FAK/Src or PI3K/Akt signaling pathways." (PMID 33513979, 2021). "These cancer cells, derived from ametastatic clear cell renal carcinoma, remodel the biomimetic matrix,with significant gene upregulation of collagen IV (COL IV) and LOX, a key enzyme driving cross-linking ofcollagen proteins." (PMID 39398183, 2024). "An increase in LOX mRNAand/or protein also has been observed in breast, head and neck squamous cell, prostatic and clear cell renal cell carcinoma, compared with their normal or non-aggressive neoplastic counterparts." (PMID 23425977, 2013).
lung adenocarcinoma (9 papers, 2013 to 2022). A carcinoma that arises from the lung and is characterized by the presence of malignant glandular epithelial cells. "In this study, we confirmed the association between LOX expression and lung adenocarcinoma poor prognosis." (PMID 29472856, 2018). "Increased LOX secretion after RT was also observed in vivo in a lung adenocarcinoma xenograft model." (PMID 27064581, 2016). "In vitro, RT increases LOX secretion in a dose-dependent manner in several tumor cell types (lung adenocarcinoma, colon carcinoma, glioma, vulva cancer, breast adenocarcinoma), which in turn promotes cancer cell invasion." (PMID 27064581, 2016). "Furthermore, TCGA Research Network7 also indicated that there might be a correlation between EGFR and LOX mRNA expression in lung adenocarcinoma patients." (PMID 29472856, 2018). "Interestingly, we noted increased secretion of both active LOX enzyme and inactive LOX pro-enzyme by human A549 lung adenocarcinoma cells in response to increasing doses of IR, with cells treated with 10 Gy of IR secreting approximately 15 times more active LOX enzyme than control cells." (PMID 25052686, 2014). "Meanwhile, LOX gene, as a key downstream sensor of XBP1, can block XBP1-induced cell proliferation by knocking down the expression of LOX, suggesting that XBP1 can regulate the proliferation of lung adenocarcinoma cells through LOX." (PMID 35559240, 2022). "The findings by Zeltz and coworkers in lung adenocarcinoma and by us in cSCC demonstrate a link between α11 and ECM crosslinking by LOX and LOXL enzymes but also imply that the molecular mechanisms whereby α11β1 reorganizes the ECM vary by tumor and CAF subtype." (PMID 36003785, 2022). "In further exploration, data showed that influence of LOX expression on the survival of lung adenocarcinoma patients is independent of gender and smoking history." (PMID 29472856, 2018). "Recently, based on bioinformatics study, we found lysyl oxidase (LOX) overexpression is closely related to the survival of lung adenocarcinoma patients but not squamous cell carcinoma patients." (PMID 29472856, 2018). "Here, we found that LOX overexpression is closely related to the survival of lung adenocarcinoma patients but not squamous cell carcinoma patients." (PMID 29472856, 2018). "In contrast to previously investigated HIF-1-mediated LOX-secretion in response to hypoxia, IR-induced LOX secretion did not result from increased LOX-transcription in the A549 lung adenocarcinoma cells." (PMID 25052686, 2014).
osteosarcoma (9 papers, 2016 to 2026). A usually aggressive malignant bone-forming mesenchymal neoplasm, predominantly affecting adolescents and young adults. "LOX activity has been associated with fibrosis and the pathology of certain connective tissues diseases and osteosarcoma." (PMID 38183136, 2024). "On the other hand, LOX appears to act as a tumor suppressor in human osteosarcoma and NPC cell lines, and decreased LOX activity was noted in fibrosarcoma, rhabdomyosarcoma and choriocarcinoma cell lines." (PMID 26882568, 2016). "In recurrent osteosarcoma, significant infiltration of CAFs has been reported; moreover, these CAFs exhibited high expression of lysyl oxidase (LOX), which could induce TAM polarization and thus reshape the tumor immune microenvironment." (PMID 40453088, 2025). "Furthermore, researchers identified LOX expression was significantly increased in recurrent osteosarcoma CAFs compared to primary osteosarcoma, and targeting LOX of CAFs is an effective treatment for recurrent osteosarcoma." (PMID 39251966, 2024). "We also observed in the gene expression analysis that genes that are bonafide targets of YAP such as BDNF, DYN3, CTGF LOX and CYR61 have reduced expression upon TZD treatment only in osteosarcoma cells." (PMID 27528232, 2016). "Targeting LOX in CAFs may offer a promising strategy for remodeling the TME and improving outcomes in recurrent osteosarcoma." (PMID 40940809, 2025). "Furthermore, their research characterized a distinct LOX-high-expressing CAF phenotype, demonstrating its essential role in osteosarcoma progression." (PMID 40380260, 2025). "Moreover, LOX inhibitor β-aminopropionitrile (BAPN) could effectively suppress osteosarcoma migration and promote apoptosis, and targeting LOX in CAFs in this way has demonstrated promising efficacy in treatment of recurrent osteosarcoma." (PMID 40453088, 2025).
anaplastic thyroid cancer (8 papers, 2016 to 2023). "MiR-30a inhibits cell invasion, migration potential, EMT, and metastatic potential by binding and negatively regulating expression of its target gene, lysyl oxidase (LOX), which is associated with higher mortality in undifferentiated thyroid carcinoma." (PMID 32596158, 2020). "We recently discovered that LOX was involved in anaplastic thyroid cancer (ATC) progression and metastasis, and higher expression of LOX was associated with lower survival rates in patients with differentiated thyroid cancer." (PMID 27296552, 2016). "Similarly, knocking out LOX and inhibiting LOX activity in Anaplastic Thyroid Cancer (ATC) cells can significantly reduce cell invasion, migration and metastasis in vitro and in vivo." (PMID 34595188, 2021).
endometriosis (8 papers, 2013 to 2025). The growth of functional endometrial tissue in anatomic sites outside the uterine body. "In patients with endometriosis-associated infertility, high LOX expression was observed in the endometrial epithelium, and LOX overexpression led to increased gene expression related to fibrosis and ECM remodeling." (PMID 39877633, 2025). "High LOX expression was observed in endometrial epithelium of patients with endometriosis-associated infertility, and overexpression of LOX increased the expression of genes related to fibrosis and ECM remodeling." (PMID 35246120, 2022). "Presently in endometriosis, lysyl oxidase (LOX) isoforms and Lipocalin2 have been tenuously linked to EMT, which would allow the epithelial cells to gain the necessary migratory and invasiveness properties to take root outside of the uterine cavity." (PMID 28725636, 2017). "Aberrant collagen reorganization and elevated lysyl oxidase levels have also been observed in endometrial pathologies, such as endometriosis." (PMID 40875056, 2025). "Aberrant collagen reorganization and elevated lysyl oxidase levels has also been observed in endometrial pathologies, such as endometriosis." (PMID 40196626, 2025). "LOX gene expression is well established as a biomarker of many carcinomas and is upregulated in endometriosis tissue samples collected from humans as well as in an animal model of the disease." (PMID 34202354, 2021). "Silencing LOX and PTX3 expression using small molecules is a potential treatment strategy for reducing cell migration, invasion, and proliferation, especially in deep infiltrating endometriosis with KRAS and PIK3CA mutations." (PMID 34202354, 2021). "Activation of EMT by the dysregulation of the Wnt-signaling pathway has been implicated in the pathogenesis of adenomyosis, while LOX isoforms and Lipocalin 2 are the main inductors of EMT that have been implicated in the pathogenesis of endometriosis at this time." (PMID 28725636, 2017). "Our findings suggest that inhibition of LOX and PTX3 may be an alternative therapeutic strategy to reduce the incidence of endometriosis." (PMID 34202354, 2021). "Thus, inhibition of KRAS/PIK3CA, or their downstream targets such as LOX or PTX3 inhibitors, might be clinically effective in progestin-resistant endometriosis-related pain." (PMID 38666954, 2024). "Therefore, LOX and PTX3 may be potential therapeutic targets for aggressive endometriosis." (PMID 34202354, 2021).
head and neck squamous cell carcinoma (8 papers, 2018 to 2025). A squamous cell carcinoma that arises from any of the following anatomic sites: lip and oral cavity, nasal cavity, paranasal sinuses, pharynx, larynx, and salivary glands. "There is emerging evidence of up regulation of LOX expression, in many types of tumors, e.g., breast, prostate, as well as head and neck squamous cell carcinomas, suggesting its role in carcinogenesis." (PMID 35054220, 2021). "Up-regulation of LOX mRNA and protein expression has been observed in various cancer types, including head and neck squamous cell carcinoma (HNSCC), breast cancer, colorectal cancer, and prostate cancer." (PMID 39430913, 2024). "Meanwhile, ammonium tetrathiomolybdate (TM), acting as copper chelator, has been shown to suppress LOX activity, cell proliferation, and the bone destruction behavior of head and neck squamous cell carcinoma (HNSCC)." (PMID 33371259, 2020). "LOX expression is enhanced in various tumors, including head and neck squamous cell carcinoma (HNSCC), and breast and colorectal cancers, and is associated with poor disease-free and overall survival." (PMID 29732010, 2018). "Similarly, TM also reduces the expression of nuclear factor-κB ligand (RANKL) in osteoblasts and osteocytes by inhibiting LOX activation, thereby reducing metastatic bone destruction due to head and neck squamous cell carcinoma (HNSCC)." (PMID 36293126, 2022).
lymph node metastasis (8 papers, 2014 to 2025). "LOX expression was associated with lymph node metastasis, distant tumor metastasis, and poor prognosis in GC patients, and the integrated analysis supported LOX as a specific diagnostic and prognostic biomarker for GC patients." (PMID 40396123, 2025). "LOX expression was related to lymph node metastasis, tumor distant metastasis and poor prognosis in GC." (PMID 36202905, 2022). "Our results indicated that the expression of LOX was related to lymph node metastasis (OR = 3.12, 95% CI = 1.670–5.836, p < 0.001) and tumor distant metastasis (OR = 3.199, 95% CI = 1.141–8.972, p = 0.027)." (PMID 36202905, 2022). "Results of the SA revealed no changes in the significance or direction of OR in the relationship between LOX expression and gender, Lauren classification, differentiation, depth of invasion, lymph node metastasis, and tumor distant metastasis." (PMID 36202905, 2022). "For predicting lymph node metastasis in GC, the sensitivity of LOX, CEA, CA724, CA199, and CA125 was 44.12, 12.75, 21.57, 23.53, and 15.69 %, respectively, and increased to 79.41 % in combination." (PMID 25060181, 2014). "For predicting lymph node metastasis in GC, the sensitivity of LOX expression was 44.12 %, and this increased to 56.52 % for predicting peritoneal metastasis." (PMID 25060181, 2014). "In lymph node metastasis and peritoneal metastasis in GC, the rate of LOX overexpression was 44.12 and 56.52 %, respectively, in the current study." (PMID 25060181, 2014). "Overall, the sensitivity of LOX for predicting metastasis in GC (lymph node metastasis and peritoneal metastasis) was 47.97 %." (PMID 25060181, 2014). "In summary, we found that LOX is a correlative tumor biomarker for GC with lymph node metastasis and peritoneal metastasis in a Chinese population." (PMID 25060181, 2014). "Our meta-analysis combining seven clinical studies showed that LOX expression was associated with lymph node metastasis and tumor metastasis of GC patients but not correlated with gender, tumor differentiation, Lauren classification, and tumor depth of invasion." (PMID 36202905, 2022). "LOX expression was related to lymph node metastasis and tumor distant metastasis in GC patients, but not to gender, tumor differentiation, Lauren classification, or tumor depth of invasion." (PMID 36202905, 2022). "The combined use of LOX with CEA, CA724, CA199, and CA125 could increase the sensitivity of predicting lymph nodes metastasis and peritoneal metastasis in GC." (PMID 25060181, 2014). "Combining LOX with CEA, CA724, CA199, and CA125 could increase the sensitivity of predicting lymph nodes metastasis and peritoneal metastasis in GC." (PMID 25060181, 2014). "The correlations between α-SMA or LOX expression with patient age, sex, tumor location, lymph node metastasis, distant metastasis and pathological grade could not be identified." (PMID 34930321, 2021).
myelofibrosis (8 papers, 2020 to 2025). A partial or complete replacement of the bone marrow stroma by fibrous tissue. "In a GATA-1-deficient myelofibrosis model, LOX overexpression drives ECM buildup and marrow fibrosis, which BAPN can mitigate." (PMID 40661776, 2025). "Elevated LOX activity in the marrow significantly contributes to myelofibrosis, with human myeloproliferative neoplasms showing heightened expression of several LOX isoforms." (PMID 40661776, 2025). "The use of a LOX inhibitor (BAPN) to decrease reticulin fibers supports LOX’s role in myelofibrosis development." (PMID 37746306, 2023). "The pan-LOX inhibitor PXS-5505 was granted orphan drug designation for myelofibrosis in mid-2020, and trials with this agent have begun in several cancers, including liver and blood; results are not yet available (ClinicalTrials.gov NCT04676529, NCT05109052)." (PMID 36066973, 2022). "Increased LOX was found to contribute to myelofibrosis in bone marrow biopsies of patients with myeloproliferative neoplasms, and the link between LOX and PDGF was further explored." (PMID 32708046, 2020). "A novel small molecule pan-lysyl oxidase inhibitor, PXS-5505, currently in clinical development for myelofibrosis treatment was evaluated using in vivo rodent models resembling the fibrotic conditions in SSc." (PMID 35628342, 2022). "One such inhibitor is PXS-5055, which reduced LOX and LOXL-2 activity when administered to myelofibrosis patients that had developed a resistance to ruxolitinib in a phase 1 trial." (PMID 33738462, 2020). "In addition, we found Lysyl oxidase (Lox), a key protein for ECM organization and a novel therapeutic target for primary myelofibrosis, to be more abundant in the FLEF relative to BMEF." (PMID 38555405, 2024).
oral squamous cell carcinoma (8 papers, 2021 to 2025). "LOX overexpression and copper‐induced LOX activity promote angiogenesis and proliferation in oral squamous cell carcinoma cells." (PMID 38804588, 2024). "Conversely, the upregulation of LOX increased the proliferation capacity and induced angiogenesis in oral squamous cell carcinoma (OSCC) cells." (PMID 34595188, 2021). "Conversely, in oral squamous cell carcinoma (OSCC), CAFs secrete small extracellular vesicles (sEVs) enriched in lysyl oxidase (LOX), which triggers collagen crosslinking and EMT via the p‐focal adhesion kinase (FAK)/p‐paxillin/YAP axis." (PMID 40656546, 2025).
osteoporosis (8 papers, 2014 to 2023). A condition of reduced bone mass, with decreased cortical thickness and a decrease in the number and size of the trabeculae of cancellous bone (but normal chemical composition), resulting in increased fracture incidence. "These LOX inhibitors have shown anticancer effects in preclinical studies, but long-term use can cause aortic damage and osteoporosis, limiting their clinical application." (PMID 37560476, 2023). "The downregulation of the OCM metabolite HCys and an associated epigenetically mediated stimulation of LOX could explain the beneficial effects of statins and bisphosphonates in osteoporosis." (PMID 25978957, 2015). "It was suggested that osteoclast LOX might be an early therapeutic target for fetal-originated osteoporosis induced by PDE." (PMID 37095518, 2023). "Bisphosphonates are common medications used to treat osteoporosis and may suppress bone metastasis by inhibiting LOX." (PMID 27147578, 2016).
sarcoma (8 papers, 1994 to 2023). A usually aggressive malignant neoplasm of the soft tissue or bone. "For instance, laminin A4 (a component of the ECM) is associated with metastasis in soft sarcoma cells and is supported by the upregulation of LOX, which remolds the ECM of sarcoma cells." (PMID 34815382, 2021). "Cumulative survival curves showed that a higher LOX expression was correlated with a significantly poorer prognosis of sarcoma via TIMER database." (PMID 35966586, 2022). "LOX was significantly associated with CD8+ T cells and macrophages infiltration, and EMT states of sarcoma." (PMID 35966586, 2022). "EWS/FLI interacts with the NuRD complex to mediate transcriptional repression of the Ewing sarcoma tumor suppressor Lysyl oxidase (LOX)." (PMID 30559927, 2018). "Biologically active molecules related to the composition of the microenvironment, such as LOX, have been shown to be up-regulated in soft sarcoma cells." (PMID 26055407, 2015). "Downregulation of LOX also inhibited growth and increased ROS production in sarcoma cells." (PMID 37874682, 2023). "TIMER database was used to investigate the role of LOX in the prognosis of sarcoma." (PMID 35966586, 2022). "Our study confirmed that LOX might contribute to poor prognosis in sarcoma patients." (PMID 35966586, 2022). "Therefore, LOX was associated with immune infiltration levels and EMT states of sarcoma, which may be a new target for OS treatment." (PMID 35966586, 2022). "LOX has significant positive correlations with infiltrating levels of CD8+ T cells (r = 0.16, p = 1.34e-02) and macrophages (r = 0.209, p = 1.24e-03) in sarcoma via the TIMER database." (PMID 35966586, 2022).
type 2 diabetes (8 papers, 2014 to 2025). "Prior research observed a close association between LOX expression and histologic alterations in early-stage DN in type 2 diabetes male ZDF rat models." (PMID 38390397, 2023). "A more recent study demonstrated that 12/15-LOX is implicated in peripheral neuropathy in mice with type 1 and early type 2 diabetes and that HFD-induced early type 2 diabetic mice exhibit LOX upregulation in the sciatic nerve and spinal cord, as well as 12(S)-HETE accumulation." (PMID 25404943, 2014).